IFNG (interferon gamma)
Diseases named in the same sentence as IFNG in open-access papers (continued):
Sharing a sentence is not in itself a finding about the gene and the disease.
cystic fibrosis (13 papers, 2012 to 2025). Autosomal recessive disorder caused by pathogenic variants in the CFTR gene (cystic fibrosis transmembrane conductance regulator), which encodes a chloride and bicarbonate channel expressed in epithelial cells, and follow the diagnosis criteria. "Chronic P. aeruginosa biofilm infections in cystic fibrosis patients are dominated by a Th2 response with increased and decreased levels of IL4 and IFNγ, respectively, suggesting that P. aeruginosa biofilms persist by reducing host proinflammatory responses to infection." (PMID 32903626, 2020).
gastric tumor (13 papers, 2017 to 2025). "Transient IFNγ exposure caused stable repression of TFF1, a gastric tumor suppressor frequently lost in H. pylori-associated cancer." (PMID 41573568, 2025). "Strikingly, NK cells strongly induced an inflammatory response in response to ZL-1211 treatment, including increased IFNγ, TNFα, and IL6 production, and were recruited into tumor microenvironment in patient-derived gastric tumors expressing CLDN18.2 upon ZL-1211 treatment to lyse the tumor cells." (PMID 36922936, 2022). "H. pylori HopQ can inhibit interferon-gamma (IFN-γ) secretion of CD4 cells and suppress T or NK cell cytotoxicity by interacting with CEACAM1, and the inhibition of immune cells may help protect developing gastric tumors from immune cell attack." (PMID 36362445, 2022). "IRF7, SIM1, IFNG, and HNF1A were predicted to be upstream regulators of the higher expressed genes in the EBV negative gastric tumors involved in cellular movement, inflammatory response, and immune cell trafficking." (PMID 31584998, 2019).
Graves disease (13 papers, 2016 to 2025). Graves' disease is an autoimmune disorder that leads to overactivity of the thyroid gland (hyperthyroidism).It is caused by an abnormal immune system response that causes the thyroid gland to produce too much thyroid hormones. "Additionally, cytokines such as Interferon gamma have been identified in both Graves’ disease and the SARS-CoV-2 infection." (PMID 36237182, 2022).
leptospirosis (13 papers, 2012 to 2025). A contagious bacterial infection caused by spirochetes of the genus Leptospira. "The contribution of both TLR4 and TLR2 in leptospirosis pathogenesis was observed in DKO mice by showing dramatically low mRNA expression of IFNγ and iNOS, compared with WT mice." (PMID 39729468, 2024). "The interferon-gamma (IFN-γ) expression level has been verified to be very low in patients who have leptospirosis." (PMID 24130911, 2013). "Notably, we observed the secretion/mRNA expression of several cytokines (IL6, IL8, IL-1β, TNFα, IFNγ, IL10, CCL2/MCP-1, CCL10, COX2, CXCL1/KC, CXCL2/MIP2) and immune effectors (hBD2, iNOS, Fibronectin, Oxygen, and Nitrogen reactive species) as key aspects of host TLR2 responses during leptospirosis." (PMID 39729468, 2024).
lymph node metastasis (13 papers, 2007 to 2026). "As observed, the expression of IFNG was negatively associated with lymph node metastasis (P = 0.026), while a high-risk score was significantly associated with increased age (P = 0.008)." (PMID 33160404, 2020).
mesothelioma (13 papers, 2013 to 2022). A usually malignant and aggressive neoplasm of the mesothelium which is often associated with exposure to asbestos. "Moreover, the PDT-based DC vaccine led to a significant increase in IFNγ+ T cells infiltered within mesothelioma, as determined by flow cytometry and immunohistochemistry." (PMID 32120810, 2020). "A dampened effector response (IFNα2, IFNγ, MIP1α, TNFα and TNFβ) was detected in NSCLC PE, but not mesothelioma or benign PE." (PMID 31741710, 2019).
Pancytopenia (13 papers, 2012 to 2025). An abnormal reduction in numbers of all blood cell types (red blood cells, white blood cells, and platelets). "Both are cytokine-driven and characterized by progressive fever, shock, organ failure, pancytopenia, liver dysfunction, and coagulopathy, and usually attributed to excessive IFNγ production." (PMID 37228668, 2023). "The mechanisms of pancytopenia with HGA are unclear, but some evidence points to pathogen activation of macrophages by proinflammatory cytokines, such as IFNγ in tissue sequestration or destruction." (PMID 37228668, 2023).
respiratory failure (13 papers, 2009 to 2025). The significant impairment of gas exchange within the lungs resulting in hypoxia, hypercarbia, or both, to the extent that organ tissue perfusion is severely compromised. "IP-10, a chemokine that is secreted in response to Interferon Gamma, has been shown to predict risk of progression to severe respiratory failure or death from COVID-1928." (PMID 41339723, 2025). "The aim of this study was to evaluate MR-proADM and in vitro IFNγ production as prognostic markers of mortality in patients with COVID-19 pneumonia and respiratory failure at hospitalization." (PMID 36016305, 2022). "CRS is associated with elevated serum levels of pro-inflammatory cytokines, including interferon gamma (IFN-gamma), TNF, IL-6 and IL-10, which contribute to a systemic hyper-inflammatory syndrome characterized most commonly by fevers, hypotension and hypoxemic respiratory failure." (PMID 34680329, 2021). "Interestingly, although neutrophils are recruited to the lung parenchyma in response to CCL3 via coordination by IFNγ, these cytokines alone clearly are not sufficient to induce the inflammatory state that ultimately promotes lung damage and respiratory failure." (PMID 19298652, 2009). "Interestingly, weight loss is sustained among the mice overexpressing CCL3 while receiving supplemental IFNγ over the 9 day examination period, but, despite the substantial inflammatory response, we observe no progression to respiratory failure up to and including t = 14 days." (PMID 19298652, 2009).
scleroderma (13 papers, 2012 to 2024). Scleroderma is a rare autoimmune connective tissue disorder characterized by abnormal hardening of the skin and, sometimes, other organs. "Whether inhaled interferon-gamma could be useful in the long term in patients with IPF or scleroderma-associated interstitial lung disease deserves a rigorously evaluation in specific trials." (PMID 23915374, 2013). "Second, sub-cutaneous interferon-gamma has been evaluated in the past in a randomized controlled multicentre trial in patients with scleroderma." (PMID 23915374, 2013). "Interferon gamma (IFN-Υ) is a dimerized soluble cytokine, which has a strong inhibitory effect on collagen synthesis by normal dermal and scleroderma fibroblasts in vitro." (PMID 34640533, 2021). "Moreover, studies in a scleroderma model demonstrate stimulation of B cells with the ECM component hyaluronan activates TLR2 and TLR4 and results in inflammatory cytokine secretion, including IL-6, TNFα, and IFNγ." (PMID 34381449, 2021). "In adult SSc, IL-13+, and not IFNγ+, CD8+CCR10+ cells appear to be the skin homing cell type that propagates disease, emphasizing possible biological differences in scleroderma phenotypes: a more inflammatory, TH1/TC1 phenotype in LS and a more fibrotic, TH2/TC2 phenotype in SSc." (PMID 31114575, 2019).
septic shock (13 papers, 2011 to 2025). Shock caused by infection; frequently caused by gram negative bacteria, although some cases have been caused by other bacteria, viruses, fungi, and protozoa; characterized by fever, chills, tachycardia, tachypnea, and hypotension. "However, in septic shock patients, the correlation between IFNγ and IL-12 (p70) with CETPI, IL-1β, TNF-α, IL-6, IL-8, and IL-10, were not significant." (PMID 36536294, 2022). "In our case (septic shock), predictive enrichment basing solely on the supportive measurement (vasopressor requirement) was not sufficient and we needed to monitor the immune status (by the cytokines IFNγ and IL10)." (PMID 33767693, 2021). "Experimental evidence indicates that inhibiting the production of IL-12, interferon-gamma (IFN-γ), and TNF-α with the combination of IL-10 and LPS is protective in septic shock." (PMID 34692364, 2021).
T cell lymphoma (13 papers, 2017 to 2026). "Previous studies demonstrated that EBV-related latent membrane protein 1 (LMP1) and interferon-gamma (IFN-γ) may upregulate PD-L1 in NPC and NK/T cell lymphoma." (PMID 31664962, 2019). "In case 3, no CD4+/CD8+IFNγ+ SARS-CoV-2-specific T-cells appeared despite VST treatment, which could be explained by the relapse of T-cell lymphoma, causing a long-term immunosuppressive state." (PMID 37414968, 2024).
trachoma (13 papers, 2009 to 2025). "IFNG was strongly upregulated in association with C. trachomatis infection, consistent with previous findings in trachoma endemic populations." (PMID 28966918, 2017). "This may be of relevance to trachoma, as Th1 responses (characterized by increased IFNγ) are thought to be associated with a less scarred outcome, which could conceivably be partly mediated through suppression of S100A7." (PMID 23285311, 2012). "For example, poor facial cleanliness and presence of flies are risk factors for active trachoma, while genetic polymorphisms in TNF-α, IFNγ, IL-10, IL8, and CSF2 have been linked to risk of trachomatous scarring." (PMID 37287960, 2023). "No SNP(PEMMAX < 0.01) was detected in any of thegenes IL8, IL10, CSF2, IFNG, HP, CCL8 or MMP9; all of which had beenpreviously reported to associate with trachoma." (PMID 26616738, 2015). "Despite considerable efforts, the mechanisms of protective immunity in trachoma remain elusive, although data from animal models suggest these involve IFNγ-dependent CMI responses." (PMID 23457650, 2013). "It has been shown that peripheral blood mononuclear cells from individuals where trachoma is endemic proliferate and produce IFNγ, in response to chlamydial antigens, and these responses were weaker in subjects with trachomatous scarring when the antigens were absent." (PMID 28678871, 2017). "In cases of active trachoma without detectable Ct, levels of IFNγ are not notably elevated, suggesting a swift regulatory response once the infection has cleared." (PMID 39203386, 2024). "The relative absence of IFNG is consistent with previous transcriptome and targeted gene expression results in Ethiopian and Tanzanian adult trachoma cases with scarring or trichiasis." (PMID 31552195, 2019).
typhoid fever (13 papers, 2014 to 2025). A bacterial infectious disorder contracted by consumption of food or drink contaminated with Salmonella typhi. "We assessed interferon-gamma (IFN-γ) responses via enzyme-linked immunosorbent spot (ELISPOT) to a number of S. Typhi antigens in samples from humans with S. Typhi bacteremia and typhoid fever in Bangladesh." (PMID 24615129, 2014). "Patients with neutralizing auto-Abs against interferon-gamma (IFN-γ) are mostly vulnerable to disseminated infections with non-virulent mycobacterial species and invasive non-typhoid salmonellosis." (PMID 36821021, 2023).
unstable angina (13 papers, 2012 to 2025). "Th1 type, especially interferon-gamma (IFN-γ), has a prominent role in the initiation of CAD and transforming stable angina to unstable angina via macrophage activation, weakening of the atherosclerotic plaque's fibrous cap and plaque rupture." (PMID 32775466, 2020).
acute coronary syndrome (12 papers, 2016 to 2025). Signs and symptoms related to acute ischemia of the myocardium secondary to coronary artery disease. "RSV has been demonstrated to impact the adaptive immune response, as indicated by a reduction in the expression of TNF-α and interferon gamma (IFN-γ) in lymphocytes in individuals diagnosed with acute coronary syndrome." (PMID 40430469, 2025). "Specifically, elevated concentrations of proinflammatory cytokines, such as interleukin-1 beta (IL-1β), tumor necrosis factor-alpha (TNF-α), and interferon-gamma (IFN-γ), are associated with the increased risks of acute coronary syndrome." (PMID 39201047, 2024). "A pathologic increase in inflammatory cytokines, IFNγ and TNFα, and cytotoxic enzymes, granzymes A and B and perforin, contributes to deleterious cardiovascular remodeling, seen in acute coronary syndromes, plaque instability, and stroke." (PMID 34680058, 2021). "In another study, patients with acute coronary syndrome and stable angina accumulate in blood a population of IFNγ-producing CD8+ CD56+ T-cells that contain more CD28null cells than the CD56− cells, indicating a harmful nature of CD8+ CD28null T-cells." (PMID 34680058, 2021).
African trypanosomiasis (12 papers, 2010 to 2025). "In rodent models (rat and mouse), CD8+ T cells and IFNγ contribute to immunopathology in both giardiasis and African trypanosomiasis, and the depletion of these cells is associated with enhanced survival of the host." (PMID 41147236, 2025). "TLTF was shown to be capable of inducing IFNγ production by astrocytes, suggesting a direct role of the molecule in the pathology development of sleeping sickness." (PMID 30333827, 2018). "Among these, interferon gamma (IFN-γ) has emerged as an important cytokine dictating the disease outcome during African trypanosomiasis." (PMID 28936213, 2017). "rhodesiense) and cattle (T. congolense) infection, the role of IFNγ in inducing inflammatory pathology has been confirmed in both, and IFNγ has been shown to play a major role in the actual cerebral complications that characterize human sleeping sickness." (PMID 30333827, 2018). "In African trypanosomiasis, CD8+ T cells and their secretion of IFNγ promote immunopathology through the imbalance of immune responses." (PMID 41147236, 2025). "In mouse models of human African trypanosomiasis, proinflammatory mediators like the tumor necrosis factor (TNF-α), interferon-gamma (IFN-γ), and CXC ligand 10 (CXCL10) have been crucial to parasite CNS invasion." (PMID 34158806, 2021). "It has previously been reported that T. brucei, an etiological agent of human African Trypanosomiasis that is related to T. congolense, can activate macrophages via direct stimulation through its Variable Surface Glycoprotein (VSG) as well as via induction of host IFNG." (PMID 20361029, 2010).
alopecia (12 papers, 2010 to 2025). Hair loss usually from the scalp. "Moreover, IFNγ and various other cytokines are pivotal players in alopecia." (PMID 39063064, 2024). "SALT: Severity of Alopecia Tool; ALT: alanine aminotransferase; AST: aspartate aminotransferase; CRP: C-reactive protein; IGRA: interferon gamma release assay; CPK: creatine phosphokinase." (PMID 41216101, 2025).
alveolitis (12 papers, 2005 to 2024). "Although no animal model is a perfect representation of ALI in humans, bacterial lipopolysaccharide (LPS) does induce key features such as alveolitis, neutrophil recruitment, and induction of IFNγ that mimic symptoms of human ALI." (PMID 22792238, 2012). "This response was rapid, marked by neutrophil recruitment and increases of protein in BAL fluid along with high levels of IFNγ and alveolitis." (PMID 22792238, 2012). "During the innate immune response to S. rectivirgula, T-bet regulates IFNγ and IL-17 production contributing to the severity of alveolitis." (PMID 21699708, 2011).
chronic GVHD (12 papers, 2006 to 2025). "Associated with T lymphocytes, IFNγ and TNFα are core cytokines of chronic GvHD pathogenesis, and IL-6 and IL-22 aggravate skin lesions." (PMID 39131155, 2024). "Similarly, in chronic graft-versus-host disease, allogenic IFNγ-producing Th1/Tc1 and IL-17-producing Th17/Tc17 cells are recruited by keratinocyte-derived chemokines and accumulate in the skin." (PMID 31324882, 2020). "These agents suppress key pro-inflammatory cytokines, including interferon-gamma (IFN-γ) and interleukin-6 (IL-6), downregulate antigen-presenting cell (APC) activity, and expand regulatory T cells (Tregs), thereby promoting a tolerogenic immune environment in both acute and chronic GVHD." (PMID 40722603, 2025).
clear cell renal cell carcinoma (12 papers, 2007 to 2026). "However, a recently published paper showed that in clear cell renal cell carcinoma, IFNγ expression in T cells purified from the microenvironment is associated with poor prognosis." (PMID 26384298, 2015).
dementia (12 papers, 2014 to 2025). Loss of intellectual abilities interfering with an individual's social and occupational functions. "We identified the strongest interactions between combinations of SNPs (IL-6 rs1800796, TNFα rs361525, and IFNγ rs2069705) associated with the risk of suffering from dementia." (PMID 36389080, 2022). "This study aimed to evaluate the effect of epistasis of gene cytokines such as interleukin (IL)-α, IL-6, tumor necrosis factor (TNFα), and interferon-gamma (IFN-γ) on the susceptibility to the development of dementia." (PMID 36389080, 2022). "Of the estimated genotypic pools, individuals with homozygous alleles for the IL-1α (rs1800587), IL-6 (rs1800796), TNFα (rs361525), and IFNγ (rs2069705) genes were identified in the high-risk group for dementia." (PMID 36389080, 2022). "In Mexico, less has been explored about the relationship of the genes’ pro-inflammatory cytokines released from activated microglia (IL-1α, IL-6, TNFα, and IFNγ) with dementia." (PMID 36389080, 2022). "Meanwhile, we investigate the associations between IgG N-glycan profiles and inflammation factors including anti-inflammatory (IL-4 and IL-10) and proinflammatory factors [IL-1β, IL-6, CRP, TNF-α, and interferon-gamma (IFN-γ)], which may further explain the role of IgG glycosylation in dementia." (PMID 33542243, 2021). "Similar to the TH cell frequencies, the IFNγ expression in memory cells was clearly age-specific (but not dementia-specific) with nearly twice as much IFNγ production in young controls compared to aged controls and dementia patients." (PMID 40537813, 2025).
dermatomyositis (12 papers, 2017 to 2025). Dermatomyositis (DM) is a type of idiopathic inflammatory myopathy characterized by evocative skin lesions and symmetrical proximal muscle weakness. "Pathway analysis and gene expression profiling of ANCA-negative VM muscle biopsies exhibited a marked upregulation of interferon-gamma (IFNγ)-inducible genes, with expression levels similar in magnitude (but different in nature) to those observed in dermatomyositis (DM)." (PMID 41441888, 2025). "In support of this, interferon gamma and tumor necrosis factor alpha, which are increased in IIM, can induce secretion of the CXCR3 ligand CXCL10 by muscle fibers, and CXCR3+ T cells have been identified in the muscle biopsies of polymyositis, dermatomyositis, and inclusion body myositis patients." (PMID 35371068, 2022).
diffuse large B-cell lymphoma (12 papers, 2014 to 2025). "PARP9, also known as B-aggressive lymphoma-1 (BAL1), was identified as a risk-related gene product in aggressive diffuse large B-cell lymphoma (DLBCL) and associated with interferon-gamma (IFNγ) gene expression and signalling." (PMID 39189367, 2024).
Flavivirus Infections (12 papers, 2011 to 2025). Infections with viruses of the genus FLAVIVIRUS, family FLAVIVIRIDAE. "This Th1 biased response and the associated IFNγ response are favourable because they are associated with milder disease outcomes during flavivirus infections and with a protective CD8 + T-cell response." (PMID 33514743, 2021). "Human CD4+ T cell responses to flavivirus infection display a Th1 cytokine pattern, characterized by expression of interferon gamma (IFN-γ), interleukin-2 (IL-2) and tumor necrosis factor alpha (TNF-α)." (PMID 26465323, 2015). "Thus, IFNγ may be protective in initial phases of flavivirus infection by controlling or preventing virus dissemination in the periphery." (PMID 33410731, 2021).
H1N1 influenza (12 papers, 2016 to 2025). "The H7N9, H7N7 and H5N1 infected mouse lung transcriptome also showed higher levels of CXCL13, IL-6, IFNG, IFNB1, IRF9, IRF1, and TNF compared with 2009 pandemic H1N1 virus infections." (PMID 28558796, 2017). "This may indicate a basal dysfunction in CD8+ T cell activation or increased CD8+ T cell apoptosis in SAA3−/− mice, rather than reveal a role for IFNγ signaling specifically in H1N1 influenza." (PMID 30410021, 2018).